EVL (Enah/Vasp-like)
Description:
Ena/VASP proteins are actin-associated proteins involved in a range of processes dependent on cytoskeleton remodeling and cell polarity such as axon guidance and lamellipodial and filopodial dynamics in migrating cells. EVL enhances actin nucleation and polymerization.
Synonyms: RNB6
Tractability: Antibody: its Gene Ontology location is reachable by antibodies, with medium confidence. PROTAC: ubiquitination databases record sites on it; its protein half-life has been measured.
Gene: Protein-coding gene on chromosome 14 (99,971,449 to 100,144,236, forward strand). Ensembl gene ENSG00000196405.
Subcellular location: Cytoplasm, cytoskeleton; Cytoplasm, cytoskeleton, stress fiber; Cell projection, lamellipodium
Subcellular location (Human Protein Atlas): Cytosol; Vesicles
Pathways (Reactome):
Developmental Biology: Signaling by ROBO receptors
Immune System: Generation of second messenger molecules
Signal Transduction: RHO GTPases Activate Formins
Gene Ontology:
Molecular function: protein binding; profilin binding; SH3 domain binding; actin binding
Biological process: negative regulation of epithelial cell migration; negative regulation of ruffle assembly; positive regulation of stress fiber assembly; actin filament organization; actin polymerization or depolymerization; animal organ morphogenesis; axon guidance; cell surface receptor signaling pathway; nervous system development; positive regulation of actin filament polymerization; positive regulation of cellular component biogenesis; positive regulation of cytoskeleton organization; positive regulation of supramolecular fiber organization; protein homotetramerization; regulation of actin filament organization
Cellular component: membrane; cytoplasm; cytosol; focal adhesion; lamellipodium; plasma membrane; cytoskeleton; stress fiber
Genetic constraint (gnomAD): Loss-of-function variants: 21 observed, 60.37 expected, observed/expected ratio (o/e) 0.35, 90% interval 0.25 to 0.5. The upper end of that interval is the gene's LOEUF score, 0.5, which puts it in group 2 of 6, group 1 being the genes least tolerant of losing a copy. Missense variants: 429 observed, 537.34 expected, observed/expected ratio (o/e) 0.8, 90% interval 0.74 to 0.87. Synonymous variants: 182 observed, 200.21 expected, observed/expected ratio (o/e) 0.91, 90% interval 0.81 to 1.03.
Homologues: Orthologues: chimpanzee EVL (99% identical), rat Evl (93% identical), guinea pig EVL (93% identical), mouse Evl (88% identical), dog EVL (85% identical), pig EVL (83% identical), tropical clawed frog evl (82% identical), macaque EVL (78% identical), zebrafish evla (62% identical), zebrafish evlb (61% identical), Drosophila melanogaster ena (41% identical), Caenorhabditis elegans unc-34 (13% identical), and 1 more. Paralogues in human: ENAH (53% identical), VASP (45% identical), SPRED3 (18% identical), SPRED2 (17% identical), SPRED1 (17% identical).
Diseases named in the same sentence as EVL in open-access papers:
EVL is named in the same sentence as 26 diseases in open-access papers, as found by Europe PMC text mining. Sharing a sentence is not in itself a finding about the gene and the disease. The quoted sentences say what the papers report.
breast carcinoma (12 papers, 2013 to 2025). "Overexpression of EVL is also indicative of advanced stage in breast cancer and has been implicated in malignancies due to inappropriate recombination." (PMID 31356589, 2019). "On the other hand, EVL-1 (a splice variant of EVL) seems to suppress the invasive phenotype in breast cancer by increasing actin bundling and decreasing protrusive activity of cells." (PMID 26336132, 2015). "Upregulation of EVL mRNA expression has been associated with breast cancer." (PMID 40473930, 2025). "Importantly, survival analysis showed that low EVL expression was associated with poor outcome in ER+ breast cancer in general, and in the luminal B subtype in particular." (PMID 30061623, 2018). "The genomic EVL/MIR342 locus was previously shown to be frequently methylated in colon cancer and upregulated EVL expression was reported in breast cancer." (PMID 34021250, 2021). "In glioblastoma and breast cancer, expression of EVL was higher in tumor tissues than normal tissue." (PMID 33076962, 2020). "Lower EVL expression correlates with high invasiveness and poor patient outcome in human breast cancer, and the expression of the EVL protein is significantly expressed in breast cancer-derived MCF7 cells." (PMID 26044366, 2015). "In human breast cancer Mena and EVL have been shown to be regulated at the transcriptional level contributing to invasiveness." (PMID 26336132, 2015). "Paralog-specific Ena/VASP inhibitors could have higher therapeutic potential, given the antagonistic roles of ENAH and EVL in promoting and suppressing breast cancer metastasis." (PMID 34854809, 2021). "Furthermore, the upregulation of EVL correlated with advanced stage of breast cancer, and promoted migration of MCF-7 breast cancer cells." (PMID 33076962, 2020). "In addition, EVL was closely related to the pathogenesis of breast cancer." (PMID 36983615, 2023). "Moreover, EVL overexpression was sufficient to suppress invasion in ER− breast cancer SUM159 cells." (PMID 30061623, 2018).
B cell lymphoma (4 papers, 2020 to 2023). "Given the presence of a promotor-associated CpG island for its host gene, EVL, we hypothesized that intronic miR-342-3p is a tumor suppressor co-regulated with host gene by promoter DNA methylation in B cell lymphoma." (PMID 33076962, 2020). "In B-cell lymphomas, miR-342 is silenced because of the hypermethylation of the EVL gene in its promoter region and the treatment with decitabine leads to the re-expression of miR-342 and the translation of the EVL protein." (PMID 37511303, 2023). "In primary samples of B cell lymphoma, miR-342 was found to be silenced by hyper methylation of the promoter region of the EVL gene, and 5-AzadC treatment resulted in re-expression of miR-342-3p and EVL protein." (PMID 34209162, 2021). "EVL/MIR342 was found to be methylated in 68 (68.7%) B cell lymphoma and eight (24.2%) T cell lymphoma, hence preferentially methylated in B cell lymphoma (P < 0.0001)." (PMID 33076962, 2020).
cervical cancer (3 papers, 2020 to 2023). A primary or metastatic malignant neoplasm involving the cervix. "The expression level of EVL in cervical cancer was lower than the matched normal tissue, and also lower than the expression level of cervical intraepithelial neoplasia." (PMID 36983615, 2023). "On the contrary, expression of EVL was found to be reduced in colorectal cancer and cervical cancer tissues compared with those in adjacent normal tissues, hence a tissue-specific expression of EVL in different types of cancer." (PMID 33076962, 2020).
colon cancer (3 papers, 2018 to 2021). "EVL gene is suppressed in colon cancer cells and associated with a dense methylation of CpG island in the 5’-UTR region of EVL, which is known as tumor suppressor gene." (PMID 34526970, 2021). "However, only methylation of EVL appeared to have a significant association with worse OS in TNM stage I–IV colon cancer patients (HR 2.48 95% CI 1.07–5.72; HR 1.95 95% CI 1.17–3.25; HR 1.41 95% CI 1.05–1.89)." (PMID 29564023, 2018).
renal fibrosis (2 papers, 2023 to 2025). A final common manifestation of a wide variety of chronic kidney diseases characterized by glomerulosclerosis and tubulointerstitial fibrosis. "Subsequently, we investigated the function and possible mechanism of the potential target termed Ena/VASP‐like (EVL) within the renal fibrosis process." (PMID 37537731, 2023). "Upon identification of the role of EVL in renal fibrosis, we further investigated the possible mechanism." (PMID 37537731, 2023). "Based on these findings, EVL is a potential target gene for METTL3‐mediated m6A modifications during renal fibrosis." (PMID 37537731, 2023). "Collectively, these results suggest that EVL is an important direct target gene for METTL3‐mediated m6A modifications during renal fibrosis." (PMID 37537731, 2023). "Accordingly, we identified a novel METTL3 TCM monomer inhibitor, isoforsythiaside, and demonstrated that it significantly inhibited the METTL3/EVL m6A axis, thereby preventing renal fibrosis." (PMID 37537731, 2023). "After elucidating the underlying mechanism by which METTL3 modulates renal fibrosis, we investigated the function of an identified target gene of METTL3, namely, EVL, during renal fibrosis." (PMID 37537731, 2023).
Allergy (1 paper, 2025). An allergy is an immune response or reaction to substances that are usually not harmful. "Notable genes associated with allergy, immune responses, and inflammation were found (LCK, BACH2, SATB1, LIME1, KSR1, BCL11B, TCF1, and EVL)." (PMID 41394805, 2025). "Furthermore, in IgE-mediated cow’s milk allergy, we observed that genes such as TCF7, EVL, and BCL11B could be associated with allergy remission and tolerant responses, making them potential candidates as biomarkers for CMA and its prognosis regarding recovery." (PMID 41394805, 2025). "Taken together, these findings suggest that the methylation of EVL gene may play a crucial role in the acquisition of tolerance in CMA and could serve as a potential biomarker of allergy remission." (PMID 41394805, 2025).
asthma (1 paper, 2019). "In this external cohort’s findings for atopic asthma, we identified 61% (48/79) of CpGs that replicated (FDR < 0.05 for 48 comparisons), all with consistent direction of association including multiple CpGs annotated to EVL and EPX genes for our asthma results." (PMID 31300640, 2019).
diarrheal disease (1 paper, 2020). The condition of having at least three loose or liquid bowel movements each day. "Contrary, during infections with the intracellular bacterial pathogens Shigella spp., which cause diarrheal disease in humans, VASP and the related protein Ena/VASP-like (EVL) limit bacterial spread." (PMID 32997728, 2020).
leukemia (1 paper, 2021). A malignant (clonal) hematologic disorder, involving hematopoietic stem cells and characterized by the presence of primitive or atypical myeloid or lymphoid cells in the bone marrow and the blood. "We then asked whether expression of EVL is associated with a specific subtype of leukemia." (PMID 34021250, 2021).
lymphoid leukemia (1 paper, 2021). A malignant lymphocytic neoplasm of B-cell or T-cell lineage involving primarily the bone marrow and the peripheral blood. "Moreover, EVL overexpression is associated with lymphoid leukemia in patients." (PMID 34021250, 2021). "Strikingly, we detected the highest expression of EVL in all subtypes of lymphoid leukemia, especially in T-ALL compared to healthy BM or myeloid malignancies." (PMID 34021250, 2021).
Sepsis (1 paper, 2023). Sepsis is defined as life-threatening organ dysfunction caused by a dysregulated host response to infection. "In conclusion, EVL demonstrated a stable diagnostic value for sepsis and that the downregulation of EVL may be related to disease progression in patients with sepsis." (PMID 36941583, 2023). "In addition, low EVL expression was associated with poor prognosis in sepsis." (PMID 36941583, 2023). "In conclusion, the results of these analyses suggest a mechanism by which the downregulation of EVL leads to the downregulation of HLA family genes, which leads to low monocyte antigen presentation and ultimately affects the prognostic status of patients with sepsis." (PMID 36941583, 2023).
tumor (12 papers, 2009 to 2023). "Decreased EVL mRNA expression was associated with poor OS and with tumor pathological stage and was an independent predictor of PACA patient prognosis." (PMID 33986805, 2021). "Tumor immune infiltration analysis showed that high expression of EVL was accompanied by high levels of immune infiltration." (PMID 36983615, 2023). "Downregulation of EVL expression in PC tissues reduced the effect of this anti-tumor immunity, leading to a poor prognosis for patients." (PMID 36983615, 2023). "The results showed that both mRNA and protein expression levels of EVL were up-regulated in tumor cell lines after evaluating the expression of EVL in four PC tumor cell lines (ASPC1, SW1990, BXPC3, PANC1) and one normal cell line (HPDE)." (PMID 36983615, 2023). "In gastric signet-ring cell carcinoma, the deletion of the Estrogen Receptor beta gene promotes tumor invasiveness through the mTOR-Arpc1b/EVL signaling pathway, resulting in a higher T stage." (PMID 36983615, 2023). "Enrichment analysis showed that EVL was involved in a variety of tumor-related pathways and immune system-related functional processes." (PMID 36983615, 2023). "MiR-342-3p, which is localized to chromosome 14q32, is a tumor suppressor co-regulated with its host gene Enah/Vasp-Like (EVL)." (PMID 34502399, 2021). "In conclusion, our study showed that miR-342-3p is co-regulated with its host gene EVL in NHL by tumor-specific promoter DNA methylation." (PMID 33076962, 2020). "Only the APC2 and EVL genes displayed higher methylation in the normal progression of a tumor from well to moderate to poor differentiation, with the APC2 gene showing 91%, 97%, and 100% and the EVL gene showing 75%, 77%, and 100%, respectively." (PMID 19750230, 2009). "As such, we hypothesize that EVL downregulation in PACA patients promotes disease progression via driving tumor invasion and metastasis, ultimately leading to poor patient outcomes." (PMID 33986805, 2021). "Therefore, we detected the mRNA and protein level of Arpc1b and EVL and concluded that ERβ might affect tumor development through the mTOR–Arpc1b/EVL signaling pathway." (PMID 33553141, 2020).
cancer (10 papers, 2009 to 2024). A tumor composed of atypical neoplastic, often pleomorphic cells that invade other tissues. "The identified gene sequences encode CD24 and EVL and both have documented established and/or proposed biological functions relevant to cancer cell biology." (PMID 23166783, 2012). "In addition, Enah/Vasp-like (EVL) has been implicated in cancer, cardiovascular disease, and neurological disorders." (PMID 36941583, 2023). "It is an intronic miRNA of the Enah/Vasp-like (EVL) host gene, located on chromosome 14q32, and is known to be involved in cancer as a tumor suppressor and kinase regulator." (PMID 39224604, 2024). "Ena-VASP-like (EVL), a member of the Enabled/vasodilator stimulated phosphoprotein family, is functionally expressed in various cancers." (PMID 36983615, 2023). ", among them the correlated expression of mir-126/EGFL7 and that of mir-342/EVL have been shown to play important roles in gene regulation of cancers." (PMID 19435500, 2009).
EVL also shares sentences with these, for which no sentence is quoted: breast tumors (3 papers); colorectal cancer (3); T cell lymphoma (2); atopic asthma (1); cardiovascular disease (1); cervical intraepithelial neoplasia (1); COVID-19 (1); moyamoya angiopathy (1); multiple myeloma (1); neurological disorders (1); renal diseases (1); Sezary syndrome (1); Ureteral obstruction (1).